LAG3 (lymphocyte activating 3)
Diseases named in the same sentence as LAG3 in open-access papers (continued):
Sharing a sentence is not in itself a finding about the gene and the disease.
infection (continued). "However, most of the virus-specific memory CD8+ T cells in the BM and spleen still retained highly exhausted phenotypes even more than 6 weeks after infection, as determined by the expression of multiple inhibitory receptors, PD-1, LAG-3, and Tim-3 on their surfaces." (PMID 24651250, 2014). "To this end, we stained OT-I T cells for PD-1, CTLA-4, Lag3, Tim3, and Tox1 during Lm-OVA and PbA-OVA infection and tracked their expression in the blood." (PMID 40163479, 2025). "In this context, the increase in LAG-3 expression, particularly among CD8+ T-cells, was more pronounced in individuals who subsequently experienced a breakthrough infection." (PMID 40977733, 2025). "We confirmed increased protein expression of PD-1, Lag3, and Tim3 in CD8+ T cells from lesions 2 weeks after infection." (PMID 38833303, 2024). "In previous studies, we have shown that at different stages of infection after E. multilocularis challenge, hepatic CD4+ T cells express significant amounts of LAG3; LAG3+CD4+ T cells secrete less IFN-γ." (PMID 37172058, 2023). "Subsequently, we investigated LAG3 expression on CD4+ T-cell subsets in the liver and spleen of mice after 24 weeks of infection." (PMID 37172058, 2023). "The levels of inhibitory receptors including LAG-3, PD-1, and TIGIT all increased on NK cells after infection and were partially reduced in mice receiving ART." (PMID 36282589, 2022). "Expression of PD-1, LAG-3, TOX, and Eomes was assessed in P14 cells recovered from the spleens of infected animals ∼30 d after infection." (PMID 34882194, 2022). "Upon a primary infection, priming of HCMV-specific CD8T cells corresponds with a transient expression for Tim-3, Lag-3 and 4-1BB at the surface of tet+ CD8T cells." (PMID 36532017, 2022). "As seen for TIM3 and LAG3, expression of 2B4 is significantly increased in CD8+ T cells upon infection with hMPV." (PMID 33809875, 2021). "Taken together, these studies indicate LAG3 is of great importance in the liver during HIV, hepatitis B virus (HBV), and hepatitis C virus (HCV) infection." (PMID 30653605, 2019). "Results showed that indeed CD200R expression is correlated with the acquisition of LAG3 and CD49b markers on CD4+ T cells in LdWT infection compared to LdCen−/− immunization (p = 0.0006 between LdWT and LdCen−/−)." (PMID 29915577, 2018). "48h post-infection, we detected a significant increase in the concentration of IFN-γ in the co-cultures with blood derived CD4+ T-cells where LAG-3 expression was silenced relative to those where silencing was not performed." (PMID 28880895, 2017). "Whereas, a significant decrease in the frequency of LAG-3+ occurred in silenced CD4+ T-cells from lung compared to untreated lung-derived T-cells at 24h (5-fold) and 48h (3-fold) post-infection." (PMID 28880895, 2017). "To determine the extent of CD8 T cell exhaustion in D2B6F1 and BCF1 mice, we examined PD-1, CD160 and LAG-3 expression and epitope-specific IFN-γ production during Cl-13 infection." (PMID 28715493, 2017). "The frequency of CD4+ T-cells expressing IFN-γ in both cultures increased over the 96h course of infection and this frequency was only slightly lower in the LAG-3 silenced CD4+ T-cells in comparison to the control co-cultures sans LAG-3 silencing." (PMID 28880895, 2017). "We next assessed the functional status of LAG3 expressing-hepatic CD4 T cells and 2B4 expressing-hepatic CD8 T cells in late-stage infection." (PMID 28894272, 2017). "We calculated the contribution of cells expressing PD-1, TIGIT or LAG-3 to the total reservoir by taking into account the frequency of these subsets within the CD4 compartment and their relative infection frequencies." (PMID 27415008, 2016). "TIM3, PD1, and LAG-3 were expressed on a substantial number of CD4+ and CD8+ T cells and their expression increased significantly late during infection (measured through week 44)." (PMID 26967901, 2016).
infection (continued). "A more detailed subpopulation analysis showed a noteworthy elevation in LAG-3 mRNA levels after 10 weeks of infection in various immune cell subpopulations, including plasma cells, T cells, and macrophages, as opposed to early infection." (PMID 38957797, 2024). "As the expression of immune checkpoint molecules on the DC may contribute to tolerogenic DCs inhibitory properties, we analyzed PD-1, TIGIT, LAG3, and CD244 expressions in cDCs and pDCs in the livers of mice at 24 weeks after infection." (PMID 38787028, 2024). "Since LAG-3 plays a regulatory role in immune responses, it can be suggested that LAG-3 may have a role during the period of infection with the influenza virus." (PMID 36680187, 2023). "Even though we did not look at the PD-1 or LAG3 expression in our study, we previously reported controlled expression of type I IFNs by gp96-Ig that seems to be tightly regulated after infection." (PMID 37056783, 2023). "These cells were initially characterized as CD138+IL10+ cells that exhibited increased expression of the inhibitory receptors LAG3, CD200, PD-L1, and PD-L2 as compared to CD138+IL10- cells and were the predominant source of IL-10 produced in response to infection." (PMID 38155972, 2023). "In the liver, we found a population of TRM cells expressing CD223 (LAG-3), CXCR6, and CD43 as well as high CD39 and PD-1 levels to represent more than 70% of the total liver antigen-specific CD8+ T cells upon chronic LCMV clone 13 infection." (PMID 33458613, 2021). "Moreover, EGR2 loss diminished the expression of multiple inhibitory receptors (PD-1, 2B4 and TIM3) within tetramer+ CD8+ T cells over the course of infection, while CD160 and LAG3 were either unchanged or even elevated within cKO cells." (PMID 33986293, 2021). "Since cytokine production by the CD4+ T cells upon in vitro restimulation was the only functional read out that we found significantly different, we propose that LAG-3 blockade is likely to act as a rapid and temporary boost of activated CD4+ T cells in this infection." (PMID 33519801, 2020). "Accordingly, on day 9 post-LCMV-CL13 infection, virus-specific CD8 TEFF from anti-LFA-1 Mab treated mice had markedly upregulated PD1, LAG3, and 2B4, while virus-specific CD8 TEFF from infected control mice expressed moderate levels of 2B4, but not PD-1 or LAG3." (PMID 33251934, 2020). "Moreover, expression of inhibitory receptors PD-1 and LAG3 was also regulated according to the potency of antigenic stimulation, reaching maximal levels in response to F-MLV envL128I infection." (PMID 29951052, 2018). "For instance, CD69, CD160, CD44, LAG3, and CTLA-4 expression on day 7 is unaffected in the absence of AT1R following immunization, but here we showed that the expression of these proteins is reduced by day 6 following infection." (PMID 28261571, 2017). "LAG-3 blockade has been shown to enhance CD8+ T cell function against HMPV, but also enhanced lung pathology, indicating that LAG-3 may play a role in ameliorating lung damage during infection." (PMID 38015461, 2023). "Similarly, P14 T cells expressed more TOX in MOG-GP than WT mice at 21 days after i.c. infection which was associated with an elevated expression of PD-1, TIGIT, LAG-3 but not TIM-3." (PMID 33579927, 2021). "As LAG3 has been shown to restrict lung CD4+ and CD8+ T cell responses during respiratory viral infections, we also considered whether AT2 MHCII is required for LAG3-mediated T cell suppression during infection." (PMID 34183650, 2021). "However, LAG-3 expression peaks early during infection and, unlike PD-1, seems to wane throughout the exhaustion phase." (PMID 34696381, 2021). "At 14 dpi, all infection groups showed almost identical upregulated mRNA expression profiles of PD1, PDL1, CTLA4, LAG3, and IDO1 compared with the negative control." (PMID 40459260, 2025).
infection (continued). "Immune checkpoint molecules including PD1, PDL1, CTLA4, LAG3, and IDO1 were significantly upregulated in the JBNU-22-N01-infected group compared with the negative control and VR2332 infection at 7 dpi." (PMID 40459260, 2025). "Moreover, LAG3 may enhance Treg function when the inflammatory and/or worm antigenic burden is high at a late stage of infection but not in less demanding environments and/or with the liver metacestode loads that exist in the early and middle stages of E. multilocularis infection." (PMID 37172058, 2023). "In summary, during chronic ASCs with HBeAg-negative infection, CD4+ T cells and their subsets, including Th1, Th2, Th17, Tfh, and Treg cells, showed high expressions of immune checkpoint molecules (TIM-3, PD-1, CTLA-4, and LAG-3) and decreased the secretion of cytokines." (PMID 35572697, 2022). "We tested this hypothesis using P. berghei ANKA (PbA) infection to determine the phenotype and function of activated antigen-specific CD8+CD44+ T cells not expressing LAG-3 (LAG-3neg), expressing low levels of LAG-3 (LAG-3low) or high levels of LAG-3 (LAG-3high)." (PMID 35874786, 2022). "And we were also able to demonstrate in vitro that hepatic CD4+LAG3+ T cells and CD8+2B4+ T cells actually displayed impaired effector phenotype, indicating altered functions of both subpopulations of T cells in mice which could not clear infection because of high PSC inoculum." (PMID 28894272, 2017).
hematologic malignancies (26 papers, 2015 to 2024). "In the phase 1 clinical trial NCT03219268, the efficacy of anti-LAG-3 × PD-1 BsAb Tebotelimab was explored in patients with solid tumors or hematologic malignancies." (PMID 38475778, 2024). "Apart from solid tumors, LAG-3-targeting BsAbs also exhibited promising efficacy in hematological malignancies." (PMID 38475778, 2024). "Although it is poorly defined, the role of LAG-3 in hematological malignancies has been increasingly assessed." (PMID 38203720, 2023). "Relatlimab, an anti-LAG-3 blocking mAb, is currently one of the most advanced mAbs in clinical trials targeting solid tumors and hematological malignancies." (PMID 33925565, 2021). "For all these reasons, LAG3-specific ICBs are currently being evaluated in phase I and phase II trials in a variety of solid and hematological malignancies either as monotherapy or in combination with anti-PD1 antibodies." (PMID 31623599, 2019). "Additionally, antibodies targeting other checkpoint molecules, including TIM3, TIGIT, and LAG-3, have been developed and are currently undergoing early clinical trials in patients with hematological malignancies." (PMID 39766080, 2024). "Thus, based on this preliminary data, LAG-3 appears to be a potentially effective alternative target of checkpoint inhibition for at least some treatment resistant hematologic malignancies, but further investigation is needed to optimize its use." (PMID 37920162, 2023). "Z-score analysis, which allows direct comparison across different studies and platforms independently from timescale and range of predictor variables, revealed that LAG3 axis has more influence on the clinical outcome of patients with CLL than in other hematological malignancies." (PMID 33925565, 2021). "Simultaneously, the parallel development of therapeutic antibodies targeting inhibitory molecules associated with immune exhaustion (such as PD-1, but also TIGIT, and LAG-3) has led to a revolution in oncology with dramatic benefits in a growing list of solid and hematologic malignancies." (PMID 32117816, 2020). "In addition, MGD013, a dual-affinity re-targeting antibody specific to both PD-1 and LAG-3 is being studied in hematologic malignancies (NCT03219268)." (PMID 31186046, 2019). "It would be interesting to investigate whether FGL1/LAG-3 pathway plays a role in hematologic malignancies." (PMID 31186046, 2019). "ICIs targeting PD-1/PD-L1, CTLA-4, lymphocyte activating gene 3 (LAG3), and CD47/SIRP- have been approved by the FDA for use in a range of solid tumors and hematological malignancies." (PMID 38279998, 2024). "In hematological malignancies, common immune checkpoint targets are reported mainly include PDCD1, IDO1, PD-L1, LAG3, and CTLA-4." (PMID 36061194, 2022). "The influence of LAG3 and MHC class II genes on outcome in different hematological malignancies was further analyzed using the PRECOG tool." (PMID 33925565, 2021). "Beyond the traditional checkpoint molecules, several other receptors are under investigation as therapeutic targets in hematologic malignancies—including TIM-3, LAG-3, and TIGIT." (PMID 33804869, 2021). "Ultimately, antibodies against TIM-3, LAG-3, and TIGIT are all under investigation for the treatment of various solid and hematologic malignancies." (PMID 33804869, 2021). "Antibodies against LAG-3 and TIM-3 are currently clinically tested to evaluate their effectiveness in patients suffering from advanced solid tumors or hematologic malignancies." (PMID 30233564, 2018). "PD-1, CTLA-4, lymphocyte activation gene-3 (LAG-3), and mucin-domain containing-3 (TIM-3) are T-cell exhaustion markers that function as co-inhibitory receptors with a significant role in regulating T-cell responses in hematological malignancies." (PMID 39062986, 2024). "LAG-3, TIM-3, and TIGIT blockade have shown promising activity in many hematologic malignancies." (PMID 37920162, 2023).
hematologic malignancies (continued). "We also discuss the basic research and ongoing clinical trials on emerging immune checkpoints (Galectin-9/Tim-3, CD70/CD27, LAG-3, and LILRBs) and on new targets for CAR-T cell therapy (CD22, CD33, CD123, BCMA, CD38, and CD138) for the treatment of hematologic malignancies." (PMID 31186046, 2019). "Favezelimab (MK-4280) is another LAG-3 antibody that is studied in combination with pembrolizumab (MK-3475) in the clinical trial NCT03598608 that was started in July 2018 to study and evaluate the safety and efficacy of these agents in hematologic malignancies." (PMID 37569880, 2023). "Additionally, the binding of LAG-3 to the soluble liver-secreted Fibrinogen-Like protein 1 (FGL-1) has been shown to inhibit CD8+ T cell-mediated anti-tumor effects, but the significance of this interaction in hematologic malignancies remains to be elucidated." (PMID 37920162, 2023). "However, there remains a considerable lack of data related to LAG-3 or TIM-3 expression in DLBCL, as well as other tumors, despite a number of clinical trials for anti-LAG-3 or anti-TIM-3 therapies (as single agent or combinations) in solid tumors and hematologic malignancies." (PMID 31007846, 2019).
immune dysfunction (16 papers, 2017 to 2025). "It has been reported that LAG-3 is associated with immune dysfunction/exhaustion of T cells." (PMID 28899396, 2017). "Thus, it is reasonable to speculate that LAG3 variants will increase the risk of PD in female population under an immune dysfunction condition." (PMID 31847878, 2019). "Several classical immune checkpoint molecules including PD-1, PD-L1, LAG3, and TIM3, have been shown to cause disorders of the immune system." (PMID 35186945, 2021). "Based on the weighted gene co-expression network analysis (WGCNA), the purple gene module was most negatively correlated with the grouping, TEX, CTLA-4, LAG-3, PD-L1, and immune dysfunction score, while the yellow module was most positively correlated with these markers." (PMID 39872516, 2024). "In summary, here we revealed diminished LAG3+ B cells in RA that might exacerbate the immune disorder and perpetuate the disease." (PMID 37143367, 2023). "In addition, T-cell response markers LAG3 and BLTA were also highly expressed in the high-risk subgroup, indicating that the risk model had the ability to identify potential immune disorders." (PMID 36189255, 2022). "Additionally, T-cell response markers (LAG3 and BLTA) were also highly expressed in high-risk groups, indicating that the risk model had the ability to identify potential immune disorders." (PMID 36189255, 2022). "Lymphocyte activation gene-3 (LAG-3), T-cell immunoglobulin and mucin domain-containing protein 3 (TIM-3), and T cell immunoreceptor with Ig and ITIM domains (TIGIT) are highly expressed in exhausted T cells within the TME and contribute to immune dysfunction." (PMID 41179287, 2025). "Additionally, these patients showed upregulation of immune exhaustion markers such as LAG3, PDCD1, TIGIT, CTL4, and C-ECM, TITR signatures, indicating a state of immune dysfunction." (PMID 38951896, 2024). "Another checkpoint, LAG3, which is considered an exhausted T cell marker, also showed an overexpression trend in the group with higher SRGS scores, suggesting that the SRGS owned the ability to identify immune dysfunction." (PMID 36225590, 2022). "Other immune checkpoints, such as LAG3 and TIM3, which are also considered exhausted T cell markers, exhibited a trend of overexpression in the high SRS score group in the multicohort, suggesting that SRS has the potential to identify immune dysfunction in LUAD patients." (PMID 34869385, 2021).
adenocarcinoma (11 papers, 2016 to 2025). A common cancer characterized by the presence of malignant glandular cells. "TIM-3, TIGIT, and LAG-3 show differential expression in squamous-cell and adenocarcinoma, varying by age and gender." (PMID 40647508, 2025). "Most importantly, MC38 adenocarcinoma-bearing mice treated with a combination of αPD-L1 and anti-lymphocyte-activation gene 3 (αLag-3) antibodies exhibited ~1.4-fold higher 89Zr-mCD4-Mb uptake than mice that were not responsive to therapy or sham-treated mice." (PMID 39239511, 2024). "Of these seven, LAG3 was most significant, in line with previous work showing its increased expression in non-adenocarcinomas of NSCLC." (PMID 30956762, 2019). "Immune checkpoint blockade (ICB) gene analysis further revealed significant upregulation of LAG3, PDCD1, PDCD1LG2, HAVCR2, and CD274 in the solid pattern adenocarcinomas." (PMID 38505588, 2024). "For patients with adenocarcinoma NSCLC, recurrence-free survival was worse in those with LAG3-positive TILs, compared to LAG3-negative." (PMID 37509517, 2023). "Therefore, we investigated the potential of the immune checkpoint molecules TIM-3, TIGIT, and LAG-3 in squamous-cell carcinoma (SCC) and adenocarcinoma (ADENO) of the urinary bladder." (PMID 40647508, 2025).
infectious disease (10 papers, 2014 to 2024). A disorder directly resulting from the presence and activity of a microbial, viral, or parasitic agent in humans. "Further, PD-1 and LAG-3 ICIs are also being investigated in infectious disease contexts, such as HIV25,26." (PMID 37344517, 2023). "Other less toxic antibodies, such as anti‐LAG‐3 and anti‐Tim‐3, may be better options in people with infectious diseases." (PMID 39248154, 2024). "Further, ICIs targeting PD-1 and LAG-3 have been explored in infectious disease contexts such as HIV, where ICI application has been shown to reactivate the viral reservoir as well as enhance HIV-specific conventional T cells responses, leading to a potential role in a functional cure approach." (PMID 37344517, 2023).
liver (6 papers, 2017 to 2024). "The current study, NEOpredict-Lung, aims to establish the feasibility of combining the PD-1 blocking antibody, nivolumab, and the LAG-3 blocking antibody, relatlimab, in preoperative treatment of NSCLC patients." (PMID 38689060, 2024). "We further found NOTCH3 levels in gastrointestinal tumor to correlate with markers of Dendritic cell(HLA-DPB1, HLA-DRA, HLA-DPA1, BDCA-4), Tfh(T-bet, STAT4, STAT1, TNF-α), Treg cells (FOXP3, CCR8, STAT5B, TGFβ) and T cell exhaustion (PD-1, CTLA4, LAG3, TIM-3)." (PMID 38906903, 2024).
hematologic cancers (3 papers, 2023 to 2025). "A phase one trial tested the PD-1- and LAG-3-targeting bispecific molecule tebotelimab in patients with solid tumors and hematologic cancers." (PMID 41155207, 2025).